CRP (C-reactive protein)
Diseases named in the same sentence as CRP in open-access papers (continued):
Sharing a sentence is not in itself a finding about the gene and the disease.
infection (continued). "Compared with the asymptomatic infection group and the mild infection group, CRP level in the common infection group was higher (F= 6.343, p< 0.05)." (PMID 35799744, 2022). "In clinical practice, a declining CRP is commonly used as a biomarker of improvement in the context of infection." (PMID 36394002, 2022). "The approximately 10-fold elevated concentrations of CRP found in this study thus indicate only a small degree of inflammatory activation as CRP is known to increase more than 1000-fold in the presence of infection." (PMID 36466340, 2022). "C-reactive protein (CRP) is a widely used serum inflammatory marker in patients with infections in orthopaedics." (PMID 35350520, 2022). "We identified significant risk factors affecting the development of postoperative infections in patients based on these data, including hydromorphone dosage, age, biological sex, BMI, WBC count, and CRP." (PMID 35979059, 2022). "CRP level in the common infection group was higher than that in the asymptomatic infection group and the mild infection group (F= 6.343, both p< 0.05)." (PMID 35799744, 2022). "The CRP level was also significantly higher in the patients with infection, 96.9 (49.1–198.7) mg/L, compared with 35.1 (9.8–82.2) mg/L in patients without infection (p < 0.001)." (PMID 36289943, 2022). "IL-2R correlated positively with C-reactive protein, a biomarker known for its response to infection and/or inflammation." (PMID 35248063, 2022). "C-reactive protein (CRP), the acute-phase protein, can alsoserve as the early marker for inflammatory disease or infection." (PMID 39076643, 2022). "CRP is an acute inflammatory protein and a common inflammatory indicator of infection, with unique biological characteristics." (PMID 35601429, 2022). "Blood samples taken also depicted unremarkable infection parameters such as leucocytes, C-reactive protein (CRP), and procalcitonin (PCT), and the blood cultures additionally taken showed no germs." (PMID 35799679, 2022). "Biomarkers of infection (C-reactive protein (CRP), procalcitonin (PCT), and interleukin 6 (IL 6)) were significantly elevated in NN1 as opposed to NN2." (PMID 36143827, 2022). "C-reactive protein (CRP), an acute-phase reactant of the pentraxin family, is synthesized in the liver under conditions of inflammation and infection in response to certain cytokines." (PMID 35844576, 2022). "Already in the sixties, it was proposed that mouse CRP is an opsonin contributing to innate immunity to infection with S. aureus." (PMID 35402541, 2022). "The reductions we observed in children and adults with a clinical infection (respectively 0·43 and 0·73 μmol/l) were greater than the reductions in retinol due to inflammation defined by elevated CRP and/or AGP, reported by the BRINDA collaboration." (PMID 35260210, 2022). "CRP is a valuable marker for assessing infection in neutropenic children and evaluating the effectiveness of antibiotic therapy." (PMID 35997401, 2022). "CRP is mainly produced in the liver in response to cytokines released by phagocytes under the conditions of trauma, infection, inflammation, and advanced cancer." (PMID 36266627, 2022). "One of the study's limitations was that we only evaluated CRP as a serum marker of postoperative infection." (PMID 35350520, 2022). "Recent meta-analyses have shown low sensitivity and specificity of CRP (0.75 and 0.67) as proof of infection." (PMID 35615626, 2022). "In the current study, pigs supplemented with antibiotics had reductions in neutrophils and serum concentrations of C-reactive protein and haptoglobin during the peak infection period." (PMID 35016715, 2022). "By Days 5 to 7, a number of biomarkers were available as evidence for infection including RNA copy number by qRT-PCR, abnormal clinical chemistry values (CRP, ALT, GGT, ALB), increased clotting time, and changes in cytokines/chemokines." (PMID 36298588, 2022).
infection (continued). "CRP is expressed in the initial acute-phase systemic response of the host to infection, inflammation, or tissue injury, while MBL plays a major role as a main biological marker of host resistance during the cytokine response." (PMID 35862957, 2022). "Based on these findings, we developed a logistic regression model based on blood levels of creatinine, albumin, and CRP, as well as alcoholic etiology that predicts infection with higher accuracy than any individual laboratory parameter or the APACHE II score." (PMID 36057565, 2022). "CRP level at post-operative day three is a sensitive indicator of infection after hip fracture surgery." (PMID 35991254, 2022). "Among them, a large number of studies have reported that preoperative infection indexes, such as C-reactive protein (CRP) level, erythrocyte sedimentation rate (ESR), and calcitonin (PCT) level, are independent risk factors for postoperative infection." (PMID 35813227, 2022). "During an acute phase response, the level of CRP increases drastically within 6–8 h following the onset of infection, peaking as much as 1,000 times more than the baseline values within 48 h and then declining afterward." (PMID 36211493, 2022). "The immediate response to infection and/or tissue damage involves liver production of acute phase proteins like C-reactive protein (CRP) and serum amyloid A (SAA); fever, often triggered by the pyrogenic cytokine IL-1β; and granulocytosis." (PMID 35821823, 2022). "We also found that lymphocytopenia and high levels of CRP and D-dimer were laboratory indicators for severe infection." (PMID 35230875, 2022). "A CRP result of ≥ 140 mg/ml from the fourth post-operative day indicated post-operative infection, according to another study." (PMID 35350520, 2022). "The objective of this study was to analyze HSCT patients with fever and investigate the potential of the PCT and CRP levels in predicting and diagnosing systemic bacterial infection and the possibility of future infections." (PMID 36148158, 2022). "CRP levels increase in response to interleukin (IL)-6-mediated purulent infections, such as active TB." (PMID 36296203, 2022). "The CRP levels were high on postoperative days two, three, and four, which can help diagnose infections early and prevent adverse outcomes." (PMID 36475186, 2022). "CRP participates in acute phase response to inflammation, infection, or organ trauma in humans, increasing up to 1000-fold within 24 to 72 hours." (PMID 35620114, 2022). "This cytokine is a marker of early host infection response; its levels increase before CRP increases; it is produced by numerous cells." (PMID 34846061, 2022). "CT-scan showed a gas flap between the ilium and the iliopsoas muscle, which was primarily referred to an infection sustained by gas-producing bacteria (CRP 7.6 mg/dl, normal value < 0.5 mg/dl; ESR 54 mm/h, normal value < 20 mm/h)." (PMID 35658905, 2022). "The mean C-reactive protein levels during infection diagnosis was 8.9 mg/dL in the AO and 4.0 mg/dL in the DO group (P = .02)." (PMID 35713438, 2022). "The mean CRP value in their non-infection control group was however 21.3 mg/L, suggesting that ageing and frailty can increase serum inflammation protein levels." (PMID 35255822, 2022). "Body temperature, PCT, and CRP were less-sensitive in multiple infection studies on hematological malignancies." (PMID 36319826, 2022). "CRP values can increase more than 100 times over, which are more noteworthy than baseline values and show a functioning state of infection." (PMID 36329535, 2022). "The panel noted that despite the correlation between ESR and infection, it is generally used less commonly than CRP by Australian Infectious Diseases physicians." (PMID 35676695, 2022). "CRP level in the mild infection group was higher than that in the asymptomatic infection group (t= 2.052, p< 0.05)." (PMID 35799744, 2022).
infection (continued). "After balancing, therisk factors that potentially promote infection from mild to severe status werehypertension, CRP, urea, D-dimer, APTT, procalcitonin, and glucose." (PMID 34550036, 2022). "From a total of 51 patients, 15 patients had developed postoperative infection with CRP levels of >96 μg/mL in nine (17.6%), 46-95μg/mL in four (7.8%) and 21-45 μg/mL in two (3.9%)." (PMID 35350520, 2022). "CRP plays a critical role in inflammation and response to infection via the complement pathway and cytokine production." (PMID 35842456, 2022). "As a classical acute phase protein, CRP rises dramatically within hours of infection or incident and has been shown to activate the complement system via the classical pathway and macrophages via Fcγ-receptors." (PMID 35407564, 2022). "Low HDL and ApoA-1 levels during the infection correlate with higher levels of inflammatory markers, such as C-reactive protein (CRP) and interleukin-6 (IL-6), and also correspond with higher mortality rates." (PMID 36140421, 2022). "Previous studies have shown that elevated CRP and interleukins have a high sensitivity and specificity, and repeated CRP has also been shown to be a good parameter for confirming infection as well as adjusting treatment duration." (PMID 36233375, 2022). "Despite the negative cultures, suspicion for infection remained high due to persistent pain, abnormal physical exam, increased CRP, and radiographs consistent with ongoing infection." (PMID 35732972, 2022). "C-reactive protein (CRP), coagulation tests, and patient’s history are routinely used to predict patients at high risk of post-operative infection complications." (PMID 36154663, 2022). "The proportion of athletes with abnormal values was comparable pre- and post-infection [pre- vs post-COVID(+)incident; CRP 5.6% vs 8.7%; P = 0.40; troponin I; 5.9% vs 5.9%; P = 0.99]." (PMID 35751748, 2022). "The combination of Cefoperazone and tigecycline in the treatment of ICU infection can effectively improve the treatment effect of the disease, have a significant bacterial clearance effect, and can reduce the serum levels of CRP, WBC and PCT." (PMID 35991266, 2022). "C-reactive protein levels were also measured but due to several instances of infection, values were deemed unreliable." (PMID 35873236, 2022). "Other systemic inflammatory and infection markers such as neutrophil count, lymphocyte count, platelet count, and CRP levels were comparable among the four treatment groups in both wound models." (PMID 35705660, 2022). "CRP is synthesized in response to monocytic mediators such as IL-1 and IL-6 in the acute phase of infections." (PMID 35620114, 2022). "C-reactive protein is a useful parameter to detect and monitor post-operative infections in orthopaedic trauma surgeries." (PMID 35350520, 2022). "Due to the low number of neonatal early-onset infections (C-reactive protein > 10 mg/L and symptoms of an infection during the first 72 h of life) in our observed cohort, we were not able to analyze the direct effects of NETs/METs on neonatal infections." (PMID 36291458, 2022). "Similar effect sizes were observed when missing data was imputed, when individuals with a self-reported infection (N = 457) were excluded and when individuals with CRP ≥ 10 mg/L (N = 60) were included." (PMID 36277463, 2022). "C-reactive protein begins to rise 2–8 h after infection-induced inflammation or tissue damage, peaks at 24–48 h, and rapidly returns to normal levels as lesions subside and tissue structure and function recover." (PMID 35281240, 2022). "No patient reported potential factors that would interfere with CRP levels, such as acute or chronic inflammation, infection, or trauma." (PMID 35185894, 2022). "CRP assists with the host response to infection, including phagocytosis, complement pathway, nitric oxide (NO) release, and cytokines production, especially interleukin-6 and tumor necrosis factor-α." (PMID 35154932, 2022).
infection (continued). "CRP has been reported as a significant predictor of severe Covid-19 illness, and an early marker of infection and inflammation." (PMID 36526994, 2022). "C-reactive protein (CRP) is a widely recognized serum inflammatory marker in patients with infections.CRP is secreted by the liver in response to multiple stimuli." (PMID 35350520, 2022). "Serious infections in the GP setting had a median CRP of 8.5 mg/L (IQR < 5-28.5), in the paediatric outpatient clinic 35 mg/L (IQR 9-107) and in the ED 21 mg/dL (IQR 5-54.5)." (PMID 36333682, 2022). "In critically ill patients, SOFA scores are strong indicators of overall mortality and CRP levels are robust indicators for extent of infection, incidences of organ injury and death." (PMID 35873893, 2022). "CRP that was included in the prediction models of the study is a sign of acute inflammatory response and is often elevated after infection or tissue damage." (PMID 36017774, 2022). "CRP, an acute phase reactant, acts as a biomarker that is raised if a person develops an infection or is septic." (PMID 36475186, 2022). "The mean aspartate aminotransferase, alanine aminotransferase, lactate dehydrogenase, and C-reactive protein levels were the highest in the MrMP group, along with higher incidences of extrapulmonary manifestations and atelectasis (during and post infection)." (PMID 35054002, 2022). "CRP is synthesized by the liver in response to any type of infection and is mainly stimulated by interleukin-6." (PMID 35566746, 2022). "Commonly used parameters to determine infection status before the second stage of TSR are serum CRP and WBC counts." (PMID 36671215, 2022). "C-reactive protein levels have been of great clinical interest for early diagnosis of infection and monitoring its treatment response as they are easily measured and related to the severity of the systemic inflammatory response." (PMID 35955767, 2022). "The calculated critical levels of NEU, WBC, CRP, Urea, Albumin, and Calcium features are important levels in determining the severity of infection of the patients." (PMID 35808317, 2022). "It is well established that levels of CRP rise as a result of inflammation, trauma, or infection within 4 to 6 h and peak at around 24 h." (PMID 36006225, 2022). "The serial CRP values showed improvement in predictability of infection in comparison with single-point values." (PMID 36158418, 2022). "Overall, the prevalence of infection in the infants based on elevated CRP and AGP levels was 36.7%, with 3.32% at the incubation stage, 14.3% at early convalescence, and 18.9% at late convalescence." (PMID 36211493, 2022). "After cardiac surgery, PSP performed better than CRP and white blood cell count for the diagnosis of infection." (PMID 35207355, 2022). "Infection rates, laboratory values (CRP, leukocyte count, hemoglobin), and body temperature were recorded at these points in time." (PMID 36386723, 2022). "We also found that tDCS treatment was better than the control group in Alb, Hb, WBC, and CRP, indicating that the treatment improved the swallowing ability and resumed oral feeding, improving the nutritional status, and reducing the infection as well." (PMID 33974170, 2022). "The rise in C-reactive protein on the third and seventh postoperative days can be used as a reliable predictor of post-operative infections." (PMID 35350520, 2022). "Five cases with the plasma concentrations of CRP greater than 10,000 ng/ml were excluded since CRP over 10,000 ng/ml indicates a sign of infection." (PMID 36447174, 2022). "One of two cases preoperatively considered likely infected due to elevated PMN and CRP levels turned to a confirmed infection due to positive histology and growth of Staphylococcus warneri in the sonication fluid." (PMID 36319727, 2022).
infection (continued). "We observed that elevated CRP was common across diseases, and in disease- or multimorbidity-stratified analyses it was almost uniformly associated with greater IRR for infection death than for cardiovascular death." (PMID 35535512, 2022). "These MS-quantified markers include the C-reactive protein (CRP) and the protein serum amyloid alpha 1 (SAA1) with abundance changes linked to infection and an individual’s inflammation status." (PMID 36523653, 2022). "Serum CRP is a positive acute-phase protein produced by the liver following stimulation by IL-6 and IL-1β in response to infection, inflammation, or cancer." (PMID 36669027, 2022). "CRP and globulin are the serological indicators commonly tested in clinic, and their levels are acceptably correlated with the severity of infection and immune status." (PMID 36038872, 2022). "The difference between pre-infection serum CRP levels and ATB endpoint levels was highly statistically significant when compared (p ≤ 0.0001)." (PMID 35631065, 2022). "A serious infection with a low CRP can be explained by the fact that in the early stage of disease the inflammatory response is still developing and CRP is still low." (PMID 36333682, 2022). "Infection biomarkers such as the CRP and procalcitonin PCT were evaluated in septic patients, but they both seemed not to be specific or sensitive enough for global clinical evaluation." (PMID 36556987, 2022). "Laboratory tests revealed a white cell count of 15.300/mL (86% polymorphonuclear cells), high c-reactive protein (CRP) level of 353 mg/dl, 77,000/mL platelets, serum creatinine level of 1.38 mg/dl and urinalysis suggestive of infection." (PMID 36060400, 2022). "As an acute-phase protein, the serum levels of CRP can increase rapidly in response to tissue injury or infection." (PMID 36387380, 2022). "It is produced by T-cells and macrophages in response to a trauma or to an infection and involves hepatic CRP liberation in the second stage of the process." (PMID 36012430, 2022). "This study, therefore, aims at assessing CRP levels in post-operative orthopaedic trauma patients and determining the reliability of CRP as an early indicator of postoperative infection." (PMID 35350520, 2022). "If an ulcer is complicated with infection, the levels of infective markers, such as high-sensitivity C-reactive protein, procalcitonin, and white blood cells, will increase." (PMID 36743890, 2022). "The singular value of CRP before reimplantation as a marker for infection control in PJI has been questioned in several studies with varying results." (PMID 36671215, 2022). "In this study, specific cut-off values of PCT and CRP levels were given, which were higher than those of other site infections." (PMID 36177334, 2022). "The level of common infection-related biomarkers was evaluated, including CRP and PCT, we found an increase of CPR in 62(57.94%) patients while PCT was only increased in 27 (25.23%) patients on admission." (PMID 35211422, 2022). "An increase in C-reactive protein (CRP) level is an acute-phase reactant in infection and inflammation." (PMID 36158394, 2022). "Relevant to biomarkers, levels of C-reactive protein (CRP), an early inflammatory marker used clinically to monitor infection and inflammation, were significantly lower in blood of HAp-IP6-Ag+–Ti mice at early stages after surgery." (PMID 36319854, 2022). "CRP is a pentameric protein of 224 amino acids secreted in the bloodstream by the liver cells in response to infection and inflammatory insults." (PMID 35149284, 2022). "The value of PCT combined with CRP in the detection of early postoperative infection is higher than that of CRP when tested alone." (PMID 35813227, 2022). "We observed that serious infections tended to have higher CRP values, however serious infections with CRP < 5 mg/L were also found." (PMID 36333682, 2022). "CRP was a protein produced by the liver, which had a role as an initial marker of infection and inflammation." (PMID 35991587, 2022).